MET (MET proto-oncogene, receptor tyrosine kinase)
Diseases named in the same sentence as MET in open-access papers (continued):
Sharing a sentence is not in itself a finding about the gene and the disease.
cancer (continued). "c-MET pathway activation plays an essential role in the development/progression and drug-resistance of many cancers, and can be caused by MET protein and/or gene overexpression, gene amplification, MET exon- 14 skipping mutations and/or aberrant paracrine/autocrine HGF production." (PMID 40211189, 2025). "MET exon 14 skipping mutations are the most commonly reported oncogenic MET mutations, and >200 distinct genomic alterations have been identified by comprehensive cancer genome profiling." (PMID 40924941, 2025). "In cancer, this signaling cascade may become dysregulated through multiple mechanisms, including c-MET overexpression or gain-of-function mutations in its kinase domain." (PMID 41233563, 2025). "The MET oncogene is overexpressed in the majority of cancers, yet as it is rarely mutated, its mode of action remains unclear." (PMID 39774381, 2025). "A master regulator of these events is the MET oncogene, which is overexpressed in the majority of cancers; however, since mutations in the MET oncogene are seen only rarely in cancers and are relatively infrequent, the mechanisms that cause this widespread MET overexpression remain obscure." (PMID 39774381, 2025). "Taken together, STMN1, HGF, and MET overexpression are associated with cancer progression." (PMID 40723207, 2025). "Paradoxically, the N375S mutant exhibits decreased binding to HGF, instead conferring enhanced ligand-independent binding affinity to HER2; cancers with this mutation are insensitive to MET TKI treatment but may respond well to HER2-targeted therapy." (PMID 39858062, 2025). "MET tyrosine kinase can be constitutively activated by mutation or amplification of the gene leading to overexpression and sustained receptor signaling in human cancers." (PMID 39742369, 2024). "Besides the secondary EGFR mutations, amplification, loss, and mutation of some other cancer-related genes also contribute to gefitinib resistance, such as MET, HER2, BRAF, and PIK3CA." (PMID 38472205, 2024). "Interestingly, HPRC is the first cancer in which MET mutations, segregating from generation to generation, were identified as causal." (PMID 38652103, 2024). "Subsequent cancer multigene panel testing revealed a positive MET exon 14 skipping mutation." (PMID 38707111, 2024). "MET is an oncogene that encodes the transmembrane receptor protein MET with tyrosine kinase activity and participates in the occurrence and development of various human cancers and mediates proliferation, migration, and invasion." (PMID 39323640, 2024). "Finally, as in many RTKs, distinct cancer-associated missense mutations are increasingly mapped to the MET kinase domain." (PMID 39268701, 2024). "The diagnostic and therapeutic potential of targeting the galectin family and c-MET signaling pathways offers promising avenues for more effective treatment approaches in various cancers, potentially enhancing diagnostic accuracy and patient care in clinical practice." (PMID 39664377, 2024). "Other findings, such as FGFR2 fusions, EGFR mutations, or MET exon 14 alterations, may also help refine diagnoses, as they are highly enriched in specific cancer types." (PMID 37682776, 2024). "Considering the reported genomic alterations of MET, such as gene amplification, mutations and fusions, these unnamed transcripts provide new avenues for exploring the diverse landscape of MET dysregulation in cancer." (PMID 37697439, 2024). "Therefore, the HGF/c-MET signaling pathway has emerged as a crucial field for investigating the mechanisms underlying cancer development and identifying potential therapeutic targets." (PMID 37919751, 2023). "Research suggests that the MACC1 protein may be caused by genetic variation, which restricts c-MET expression, hence encouraging the spread of cancer cells." (PMID 36979146, 2023).
cancer (continued). "Furthermore, the growth inhibitory effect of EAHDT on Huh7 LCSCs was associated with the downregulation of c-MET-mediated downstream signaling pathways and key cancer stemness markers." (PMID 38201226, 2023). "However, in certain tumors with mutations or amplification of the MET proto-oncogene, MET itself is required for neutrophil chemoattraction and the release of nitric oxide, which in turn, promotes cancer cell killing." (PMID 37444436, 2023). "In this research work, the mutations or variations found in MET gene were explored and screened, which may have detrimental effects on human normal cellular functions, preceding different cancers, and other diseases." (PMID 37200850, 2023). "Furthermore, antibodies recognize MET, even if the intracellular part is mutated in cancer cells (METΔ14 or activating mutations in the catalytic site)." (PMID 37760640, 2023). "In addition to MET exon 14 skipping mutations, activating point mutations in the TK, JM, and extracellular domains have been reported in cancer, leading to ligand-independent receptor phosphorylation and signaling." (PMID 37296895, 2023). "In particular, strong c-MET IHC staining with a score of 3+ was consistently associated with a short OS in both univariate and multivariate analyses for patients who received anti-cancer therapy." (PMID 36969059, 2023). "The c-MET expression was also associated with a higher rate of cancer-related deaths." (PMID 38132404, 2023). "As it is conceivable that some cancers are primarily driven by the MET mutations, to date, METamp and METex14, have shown their actionability in NSCLC, such as prognosis, and expanding the therapeutic opportunities for patients without EGFR and ALK as usual alterations." (PMID 36430388, 2022). "Hyperactivity of HGF/c-MET signalling is considered a hallmark of cancer." (PMID 36591282, 2022). "Moreover, PRRX1 loss‐mediated MET also confers cancer cells with stemness, leading to drug resistance thus further explaining why PRRX1 overexpression predicts good prognosis." (PMID 35601657, 2022). "In addition, antiangiogenic therapy with sunitinib causes hypoxia decreasing the blood supply for cancer cells and this causes an upregulation of c-MET pathway." (PMID 35069735, 2022). "Studies have shown that dysregulation of MET signaling pathway including gene amplification, overexpression of the ligand and/or receptor, autocrine signaling, and paracrine signaling has been indicated as a cancer-associated mechanism." (PMID 36483096, 2022). "To explore other possible mechanisms, we attempted to analyze the correlation of BICD1 downregulation with a couple of markers involved in various pathways associated with cancer progression, including the immune checkpoint, MET, STAT, and MTOR pathways, in the TCGA LGG cohort." (PMID 34439934, 2021). "Herein, we demonstrate that small-molecule kinase inhibitor DCLK1-IN-1 strongly inhibits DCLK1 phosphorylation and downregulates pluripotency factors and cancer stem cell (CSC) or epithelial-mesenchymal transition (EMT)-associated markers including c-MET, c-MYC, and N-Cadherin in RCC cell lines." (PMID 34830884, 2021). "Based on these data, tepotinib was granted Breakthrough Therapy Designation by the FDA in September 2019 for second-line treatment of patients with metastatic NSCLC harboring MET exon 14 skipping mutations who progressed following platinum-based cancer therapy." (PMID 34425853, 2021). "Cancer-linked point mutations involving MET-stop motifs of human PX domains." (PMID 34368138, 2021). "Notably, 5′ RACE and protein expression of the novel MET isoform has been previously reported, further validating the ability of our pipeline to identify novel cancer-associated promoters." (PMID 33482911, 2021).
cancer (continued). "However, there is a need to conduct further studies on the safety and efficacy of MET TKI in patients who have failed EGFR TKI therapy and in whom one of the main causes of resistance is the selection of a cancer cell clone with MET gene abnormalities." (PMID 34945842, 2021). "Abnormal activation of the HGF/c-MET pathway and immune cell infiltration have been widely demonstrated to play an essential role in a variety of tumors, so we integrated HGF/c-MET pathway and immunoregulatory elements to analyze the underlying driving mechanisms of cancer." (PMID 34261467, 2021). "First, we analyzed the impacts of mTOR inhibition on MET-deficient cancer cells." (PMID 32764535, 2020). "In MET, missense mutations were identified in various cancer types, including ES." (PMID 32754598, 2020). "Among them, the c-MET/HGF-activated pathway is one of the most studied: its deregulation or constitutive activation is associated with cancer onset and progression, and for this reason, it has been considered as a potential target for therapeutic purpose in several solid cancers." (PMID 33212946, 2020). "It has also been shown that lactate (produced by MET/EGFR TKI-resistant cancer cells) enhances the production/secretion of HGF by cancer-associated fibroblasts, which in turn activates MET-dependent signalling pathways in cancer cells, causing adaptive resistance to MET inhibitors." (PMID 33271944, 2020). "So the actions of MET on Akt1/2 are essentially due to a loss/reduction of Akt1/2 activity since when the ratio of active Akt1/2 (phosphorylated) to total Akt1/2 levels is calculated we observed a reduction of Akt1/2 activity in cancer cells." (PMID 33108409, 2020). "Interestingly, most differentially expressed genes were identified as upregulated in MET-mutated cancers compared with MET wild-type cancers." (PMID 33437521, 2020). "The MET oncogene encodes a tyrosine kinase receptor involved in the control of a complex network of biological responses that include protection from apoptosis and stimulation of cell growth during embryogenesis, tissue regeneration, and cancer progression." (PMID 32245152, 2020). "Because increased MET signaling is implicated in the development and progression of several types of carcinoma, IQGAP1 may be a potential therapeutic target in selected malignancies." (PMID 33087447, 2020). "Thus, in cancers driven by MET amplification/overexpression or activating mutations, MET activation and downstream signaling is unlikely to be fully blocked by drugs solely targeting HGF-MET binding." (PMID 30941314, 2019). "Furthermore, experimental evidence demonstrates that an activated MET oncogene—known as a key regulator of the resistance of NSCLC to gefitinib (an EGFR inhibitor)—promotes cancer-associated thrombosis." (PMID 30959839, 2019). "In cancers, MET activation is commonly implicated in both cell proliferation and invasiveness." (PMID 31040922, 2019). "Aberrant MET tyrosine kinase signaling is known to cause cancer initiation and progression." (PMID 30208970, 2018). "As a rule, EGFR-dependent cancer cell lines that have undergone EMT as a mechanism of acquired resistance fail to exhibit previously documented molecular events such as selection for the EGFR T790 M gate-keeper mutation or MET amplification." (PMID 29458371, 2018). "Although the exact implications of this observation are less clear, our findings suggest that VUS such as the MET germline variants we reported may indeed play a unique, as yet unclear, role in the context of CS-related hereditary cancer predisposition." (PMID 29684080, 2018). "Furthermore, gemcitabine-resistant cancer cells acquire the hallmarks of EMT in association with an increment of MET phosphorylation and the expression of the stem cell marker CD (cluster of differentiation)." (PMID 30544501, 2018).
cancer (continued). "In an attempt to investigate underlying molecular mechanisms of c-MET/EGFR reduction in NRF2-silenced cancer cells, we hypothesized the potential involvement of miRNAs in the dual regulation of c-MET and EGFR." (PMID 29291022, 2017). "In a variety of cancers, furthermore, many MET mutations have also been discovered." (PMID 28061464, 2017). "Previous studies have shown that miR-199a and MET are implicated in human cancers including HCC." (PMID 27813498, 2016). "Various mutations in the MET gene were reported to be associated with cancers." (PMID 27557076, 2016). "In the current case-control study with 1032 HCC patients and 1060 cancer-free controls, we investigated whether miR-199a rs74723057 and MET rs1621 polymorphisms are associated with the risk of HCC in the population of South China." (PMID 27813498, 2016). "Our findings constitute evidence justifying further studies of the frequency of MET germline mutations in high-risk populations, the role of MET inhibitors in cancer prevention, and the use of MET-T1010I as biomarker for inclusion of patients in therapeutic studies of MET inhibitors." (PMID 25605252, 2015). "The dysregulation of HGF/MET pathway has been implicated in many kinds of cancers." (PMID 26254225, 2015). "Aberrant c-MET expression occurs in various cancers and is associated with a poor prognosis." (PMID 26225770, 2015). "The role of MET mutation in human cancer was first established in papillary renal carcinoma." (PMID 26649038, 2015). "MET gene amplification, copy number, and mutation appear to be relatively conservative biomarkers, but they may be associated with rare events in cancer development." (PMID 28536405, 2015). "However, HGF/c-MET axis has also been implicated in the regulation of cancer cell growth, angiogenesis, invasion, and metastasis." (PMID 26137493, 2015). "Mutation of the MET gene represents a rare event in cancer, but it might play a causal role in the development of certain cancers or lead to enhanced activation of MET kinase activity and confer tumorigenic properties in cells." (PMID 28536405, 2015). "Similarly, a recent report suggested that targeting MET-amplified refractory mGE cancer is associated with encouraging clinical activity." (PMID 26082439, 2015). "Preclinical studies showed that ROS1-positive cancer cells, including the G2032R variant, are sensitive to MET/VEGFR2 inhibitor foretinib, strongly suggesting that foretinib could be the drug of choice for ROS1-positive NSCLC." (PMID 24722523, 2014). "Various mutations in the MET gene are associated with carcinoma occurrence." (PMID 24957404, 2014). "Because MET p.T992I has also been found in germline DNA of individuals diagnosed with other cancers, a large-scale study to examine the penetrance and risks of all cancers in mutation carriers will be an important advance in our understanding." (PMID 21970370, 2011). "Specific inhibitors of the MET protein are currently in use in human clinical trials and may have a specific utility in preventing invasion and the metastasis of early-stage cancers in individuals with the MET p.T992I mutation." (PMID 21970370, 2011). "The crystal structures of FLT3, KIT and MET kinases have suggested that cancer mutations may destabilize the autoinhibited wild-type (WT) form." (PMID 19834613, 2009). "However, inhibitor withdrawal causes rapid MET re-phosphorylation at levels higher than those at the steady state, with the subsequent reactivation of downstream pathways and increased proliferation of cancer cells." (PMID 36697438, 2023).
cancer (continued). "However, as D-17 cells harbor mutations in several putative cancer driver genes, including a frameshift mutation in MET, one cannot exclude that the observed overexpression of MET is only one part of a concerted action leading to the high migration and invasion behavior of these cells." (PMID 37048099, 2023). "Previously, we reported that discontinuation of MET tyrosine kinase receptor inhibition causes ‘rebound’ activation of the oncogene, with a post-treatment transient hyperphosphorylation phase that culminates into a dramatic increase in cancer cell proliferation." (PMID 36697438, 2023). "In addition, our previous studies also identified the stimulatory effect of C1GALT1-mediated O-glycosylation on RTK activity such as EPHA2, integrin, and MET in several adult cancers and C1GALT1 high expression was associated with poor survival of patients in these studies." (PMID 35169131, 2022). "The activation of the HGF/MET axis is associated with a series of biological responses, such as proliferation, angiogenesis, migration, invasion, metastasis, and survival, thus contributing to the tumorigenesis, development, and progression of different human cancer types." (PMID 32435640, 2020). "Using human cancer cell lines, including Hs746T (MET-mutated/amplified), H596 (MET-mutated), and H1993 (MET-amplified) cells, as well as BEAS-2B bronchial epithelial cells, we investigated whether MET is involved in the regulation of immune checkpoint pathways." (PMID 31480591, 2019). "Interestingly, the activation of the HGF/c-MET axis may be involved in pro-tumoral microenvironment changes caused by cancer cells-released exosomes." (PMID 30642077, 2019). "MET exon 14 skipping mutations may be one of the few just been uncovered for cancers, because alternative splicing transcripts could be found quite frequently in cancers." (PMID 31369639, 2019). "Since then, altered MET functions were identified as a hallmark of several cancer types, including carcinomas, sarcomas, and brain tumors, and may occur through gene amplification, deletions, mutations, receptor overexpression, or disruption of normal paracrine signaling." (PMID 30544501, 2018). "Studies indicated that c-MET in cancer is activated through both ligand-dependent autocrine or paracrine mechanisms and ligand-independent mechanisms including gene amplification, gene translocation, activating mutations, or transcriptional upregulation of the c-MET protein." (PMID 28485003, 2017). "Also, c-MET was frequently overexpressed, mutated or amplified in many cancers." (PMID 25193856, 2014). "Interestingly, MET point mutations have been recently associated with the so-called “cancers of unknown primary origin” (CUP)." (PMID 22973229, 2012). "MET, a receptor tyrosine kinase (RTK) implicated in cancers like lung and gastric, drives cellular growth via ATP-dependent signaling, but mutations often confer resistance to inhibitors, requiring evaluation of multiple treatments." (PMID 41550255, 2026). "In summary, we engineered novel c-MET-targeted TCEs in both the taFv and scDb formats and showed their potency in vitro, thereby facilitating future translation as therapeutics for (combination) treatment of c-MET-positive cancers." (PMID 41552759, 2026). "Their downregulation, often via promoter hypermethylation, leads to excessive activation of hepatocyte growth factor/c-MET or protease-activated receptor-2/NF-κB signaling, promoting epithelial-mesenchymal transition and cancer progression." (PMID 41752136, 2026). "Hyperactivation of c-MET promotes cancer cell survival by activating pathways that help them withstand oxidative stress, contributing to drug resistance." (PMID 41019287, 2025).